IGHG4 (immunoglobulin heavy constant gamma 4 (G4m marker))
Description:
Constant region of immunoglobulin (Ig) heavy chains. Igs are membrane-bound or secreted glycoproteins produced by B lymphocytes. In the recognition phase of humoral immunity, the membrane-bound Igs serve as receptors, which upon binding to a specific antigen trigger the clonal expansion and differentiation of B lymphocytes into Ig-secreting plasma cells. Secreted Igs known as antibodies mediate the effector phase of humoral immunity by blocking the interaction of infectious antigens with cellular receptors (via the antigen-binding region) and eliciting effector mechanisms that lead to pathogen neutralization (via the constant region). The antigen-binding region is formed by the variable domain of one heavy chain paired with the variable domain of its associated light chain. Each Ig molecule has two antigen-binding sites with remarkable affinity for a particular antigen due to V-(D)-J rearrangement, somatic hypermutations and affinity maturation of the variable domains upon antigen exposure. The constant region defines the Ig isotype that perform distinct sets of effector functions. B cells diversify and rearrange their Ig constant regions through class-switch recombination, a process by which the constant region is switched from one Ig isotype to another, namely from IgM and IgD to IgG, IgA and IgE. The constant region interacts (via the fragment crystallizable, Fc) with the Fc receptors on innate immune cells to mediate humoral effector functions. Ig gamma-4 (IgG4) isotype does not elicit antibody-dependent cellular cytotoxicity (ADDC) or complement-dependent cytotoxicity (CDC). Instead it is likely involved in immune tolerance mechanisms to allergens and parasites either by blocking IgE-antigen complex formation or by directly inhibiting mast cell degranulation through Fc receptor signaling. In the context of tumorigenesis, it may participate in immunosuppressive mechanisms.
Tractability: Antibody: its Gene Ontology location is reachable by antibodies, with high confidence; UniProt places it where antibodies can reach, with medium confidence; UniProt predicts a signal peptide or a membrane-spanning region.
Gene: Immunoglobulin constant (C) gene on chromosome 14 (105,620,506 to 105,626,066, reverse strand). Ensembl gene ENSG00000211892.
Subcellular location: Secreted (Isoform 1); Cell membrane (Isoform 2)
Pathways (Reactome):
Immune System: Classical antibody-mediated complement activation; FCGR activation; Initial triggering of complement; Interleukin-4 and Interleukin-13 signaling; Regulation of Complement cascade; Regulation of actin dynamics for phagocytic cup formation; Role of phospholipids in phagocytosis
Disease: FCGR3A-mediated IL10 synthesis; FCGR3A-mediated phagocytosis
Gene Ontology:
Molecular function: antigen binding; immunoglobulin receptor binding
Biological process: adaptive immune response; antibacterial humoral response; B cell receptor signaling pathway; complement activation, classical pathway
Cellular component: blood microparticle; extracellular exosome; extracellular region; IgG immunoglobulin complex; immunoglobulin complex, circulating; plasma membrane
Homologues: Paralogues in human: IGHG2 (93% identical), IGHG1 (93% identical), IGHG3 (92% identical), IGHE (35% identical), IGHM (31% identical), IGHA1 (29% identical), IGHA2 (28% identical), IGHD (24% identical), IGLL1 (12% identical), IGLL5 (12% identical), IGHV3-48 (8% identical), IGLC1 (8% identical), and 65 more.
Diseases named in the same sentence as IGHG4 in open-access papers:
IGHG4 is named in the same sentence as 23 diseases in open-access papers, as found by Europe PMC text mining. Sharing a sentence is not in itself a finding about the gene and the disease. The quoted sentences say what the papers report.
COVID-19 (3 papers, 2021 to 2022). A disease caused by infection with severe acute respiratory syndrome coronavirus 2. "In particular, four of the shared six genes between the McClain and Lee data were immunoglobulin encoding genes: IGHG1, IGHG3, IGHG4, and IGLC2, all of which were consistently upregulated in a COVID-19 specific manner across the datasets." (PMID 35991542, 2022). "Our IPA analysis found that the IgG component genes, IGHG3, IGHG4, and IGHV3-30 are upregulated in the lungs of severe COVID-19 patients." (PMID 34899680, 2021).
Myeloma (2 papers, 2024 to 2025). "C3 IGHG4+ Myeloma cells mainly playing the role of Influencer, Monocytes Macrophages Play the roles of Receiver and Influencer." (PMID 40406148, 2025). "We classified 1501 plasma cells in MM into four distinct cell subsets, C1 IGHA1+ Myeloma cells, C2 IGHG1+ Myeloma cells, and C3 IGHG4+ Myeloma cells, in order to better understand the characteristics of plasma cells in MM." (PMID 40406148, 2025). "The results showed that KLF6, NR3C1, IRF7 and YY1 were all actively regulated in C0 IGLC3+ Myeloma Cells, C1 IGHA1+ Myeloma Cells, and JUN was actively regulated in C0 IGLC3+Myeloma Cells, C1 IGHA1+ Myeloma Cells and C3 IGHG4+ Myeloma Cells." (PMID 40406148, 2025). "We investigated the differentiation trajectories of malignant plasma cells and identified four major myeloma subpopulations: C0 IGLC3+, C1 IGHA1+, C2 IGHG1+, and C3 IGHG4+ myeloma cells." (PMID 40406148, 2025). "C2 IGHG1+ Myeloma cells and C3 IGHG4+ Myeloma cells in M3 regulatory module had relatively high regulatory activity." (PMID 40406148, 2025). "This analysis resulted in the identification of four distinct cell subsets: C0 IGLL5+ Myeloma Cells, C1 IGHG4+ Myeloma Cells, C2 MALAT1+ Myeloma Cells, and C3 IGHG1+ Myeloma Cells." (PMID 39281682, 2024). "The biological process with the highest correlation with C1 IGHG4+ Myeloma Cells was subunit; The biological process most associated with C2 MALAT1+ Myeloma Cells was biosynthetic; The biological process most associated with C3 IGHG1+ Myeloma Cells was electron." (PMID 39281682, 2024). "We next looked at the APP signaling network, and the findings indicated that monocyte/macrophages, C3 IGHG4+ myeloma cells, and C0 IGLC3+ myeloma cells had substantial relationships with one another." (PMID 40406148, 2025). "C1 IGHA1+ Myeloma cells were mainly distributed in the middle stage, namely State 2; C2 IGHG1+ Myeloma cells and C3 IGHG4+ Myeloma cells were mainly distributed in the final stage of the trajectory, that is, State3." (PMID 40406148, 2025). "The four identified cell subgroups were as follows: C0 IGLL5+ Myeloma Cells (724 cells), C1 IGHG4+ Myeloma Cells (310 cells), C2 MALAT1+ Myeloma Cells (305 cells), and C3 IGHG1+ Myeloma Cells (149 cells)." (PMID 39281682, 2024). "The results showed that C0 IGLC3+ myeloma cells had the highest differentiation potential, indicating that C0 IGLC3+ myeloma cells had the strongest proliferation ability and were naive tumor cells, followed by C1 IGHA1+ myeloma cells, C2 IGHG1+ myeloma cells, and C3 IGHG4+ myeloma cells." (PMID 40406148, 2025). "Additionally, the most activated TFs in each subgroup within the M1-M5 modules were identified as follows: MAF in the C0 IGLL5+ Myeloma Cells subgroup, LEF1 in the C1 IGHG4+ Myeloma Cells subgroup, TCF12 in the C2 MALAT1+ Myeloma Cells subgroup, and CREB5 in the C3 IGHG1+ Myeloma Cells subgroup." (PMID 39281682, 2024).
anaplastic carcinoma (1 paper, 2021). "After gene ontology analysis, it was found that plasma cell (RPS12) could potentially contribute to the development of anaplastic carcinoma, while plasma cell (IGHG4) could contribute to Burkitt lymphoma." (PMID 34485161, 2021).
colorectal cancer (1 paper, 2023). A primary or metastatic malignant neoplasm that affects the colon or rectum. "The expression of marker gene IGHG4 was found to be significantly higher in the diffuse subcluster developed from activated B cells which highly correlated with metastasis of colorectal cancer." (PMID 36752296, 2023).
colorectal tumors (1 paper, 2024). "Meanwhile, cells expressing immunoglobulins (involving IGHG4), such as B cells and IgG plasma cells, infiltrate and help control colorectal tumors." (PMID 38168288, 2024).
glioma (1 paper, 2021). A benign or malignant brain and spinal cord tumor that arises from glial cells (astrocytes, oligodendrocytes, ependymal cells). "In glioma grade IV, highly activated DEGs included STOM, IGHG4, CXCL13, MMP13, and CAPN6, while highly downregulated DEGs included JAZF1-AS1 and ELDR." (PMID 33948562, 2021).
intestinal cancer (1 paper, 2024). "Again, in human intestinal cancer, the tradeoff between IGHG4 and SFRP2 transcripts specifically where both are abundant is not detected by pairwise correlation nor by ME delineation." (PMID 38168288, 2024). "In the human intestinal cancer specimen, the broad colocalization but local anticorrelation of IGHG4 and SFRP2 may reflect the involvement of humoral immunity in combating the cancer." (PMID 38168288, 2024).
lung carcinoma (1 paper, 2022). "Notably, elevated expression levels of production of immunoglobulin-related genes IGHG4, IGKC, IGLC2, IGHG3, and PLAU were detected in the SPP1-Mφ cluster, suggesting the proinflammatory and anti-tumor functions of this cluster in lung cancer." (PMID 36008393, 2022).
proliferative diabetic retinopathy (1 paper, 2023). Advanced retinopathy due to diabetes mellitus characterized by the formation of new vessels in the retina. "Chronic inflammation has been linked to angiogenesis, suggesting IGHG4 could contribute to neovascularization in proliferative diabetic retinopathy through inflammation." (PMID 38124748, 2023).
psoriasis (1 paper, 2024). An autoimmune condition characterized by red, well-delineated plaques with silvery scales that are usually on the extensor surfaces and scalp. "In contrast, most immunoglobulin genes in psoriasis lesions were unchanged or downregulated, and only the IgG heavy constant IGHG4 was significantly upregulated in psoriasis lesions compared with HC." (PMID 37137278, 2024).
tumor (11 papers, 2022 to 2025). "The results showed that CAFs in P-LNs were associated with the high expression of NFIB, IGLC2, IGHG4, C7, and CCL19, while CAFs in tumor 3 had high expression of DIO2, LGALS1, WNT5A, NEAT1, and MMP11 in the tumor." (PMID 36569924, 2022). "Notable genes displaying similar expression patterns in AFCs and tumour cells compared with FCs included TFF3 and TG (signature genes of FCs), IGHG4 and SFRP2 (signature genes of FCs) and FN1 and SFTPA1 (signature genes of tumour cells)." (PMID 38426403, 2024). "Both the mIHC data and the validation cohort data further proved that immune‐related genes (IGHG4) were highly expressed in AFC cells, especially in tumour tissue compared with tumour adjacent tissue." (PMID 38426403, 2024). "Then, we verified the expressions of IGHG4, IGKC, APOD and MUCL1 at the protein level in tumor sections of clinical TNBC patients (HER2low, n = 5 vs. HER2neg, n = 5) by IF staining." (PMID 36998014, 2023). "The results showed that tumor cells in metastatic LN expressed high levels of IGLC2, IGHG4, and IGKC, and GO analysis showed various immune-related signaling pathways." (PMID 36569924, 2022). "In analyzing B cells in the tumor microenvironment, B cells were separated into two clusters: one termed as follicular B cell, with high expressions of MS4A1, CD79B, CD52, and another termed as plasma cell, with high expressions of IGHG1, IGHG4 and MZB1." (PMID 38443340, 2024). "Strikingly, it showed that IGHG4 and IGKC were predominantly expressed in HER2neg TNBC group (in tumor tissues containing tumor cells and mesenchymal cells), whereas APOD and MUCL1 were highly expressed in HER2low group, which were consistent with the scRNA-seq data." (PMID 36998014, 2023). "We then analyzed and marked the top 20 DEG genes in tumor core regions and found that IGHG1, IGHG3, IGHG4, IGKC, and IGLC2 (effector markers for humoral immunity) were notably downregulated in core regions, possibly indicating an immunosuppressive microenvironment (ISME)." (PMID 35673582, 2022). "Therefore, as the transitional states of the tumour cells, AFC cells may also express high‐level IGHG4‐related IgG." (PMID 38426403, 2024).
cancer (6 papers, 2022 to 2024). A tumor composed of atypical neoplastic, often pleomorphic cells that invade other tissues. "Furthermore, although IGHG4 (14q32.33) was identified as one of the most significantly down-regulated genes in three Taiwanese and one Caucasian ESCC cell lines compared with three normal tissues of esophagus, the function of IGHG4 in human carcinoma is still unclear." (PMID 36752296, 2023). "CCL15 was also increased as the pseudo-time progressed and was dominant in the end stages of the pseudo-time axis; Conversely, other key molecules such as IGHG1, IGHG3, IGHG4, IGKC, IGLC2 decreased gradually among all the carcinoma sectors in HCC1 and HCC4." (PMID 35673582, 2022).
IGHG4 also shares sentences with these, for which no sentence is quoted: blood cancer (1 paper); Burkitt lymphoma (1); escherichia coli infection (1); joint disease (1); melanoma (1); meningioma (1); polycystic kidney disease (1); preeclampsia (1); Primary immunodeficiency (1); staphylococcus aureus infection (1); systemic lupus erythematosus (1).